TLR4 (toll like receptor 4)
Diseases named in the same sentence as TLR4 in open-access papers (continued):
Sharing a sentence is not in itself a finding about the gene and the disease.
colitis (continued). "Through animal experiments, this study found that supplementation of B. tequilensis YB-2 in the diet can significantly reduce colitis induced by DSS and alleviate intestinal barrier damage in mice, and its protective mechanism may be achieved by inhibiting the TLR4/NF-κB pathway." (PMID 38998101, 2024). "However, colitis in Yod1−/− mice was still significantly more severe than that in Yod1+/+ mice after LPS administration (Fig. EV1A–I), showing that YOD1 is dispensable for TLR4 signaling in vivo." (PMID 39333628, 2024). "Additionally, melittin administration effectively corrected the heightened levels of TNF-α and IL-6 while simultaneously suppressing upstream signaling molecules such as Toll-like receptor 4 (TLR4), p38 mitogen-activated protein kinase, and NF-κB in an acetic acid-induced colitis model." (PMID 37812268, 2024). "By using a TLR4 overexpression plasmid, we found that ruscogenin treatment potentially alleviates DSS-induced colitis in mice by inhibiting NLRP3 inflammasome activation and canonical pyroptosis, and the protective effect may be related to the suppression of the TLR4/NF-κB signaling pathway." (PMID 38790951, 2024). "Notably, in DSS-induced mice colitis model, Man-CUR NYPs can reduce the inflammatory responses by modulating TLR4/NF-κB signaling pathways, alleviate oxidative stress by Nrf2/HO-1 signaling pathway, promote macrophages reprogramming and improve the favorable recovery of the damaged colonic tissue." (PMID 37679849, 2023). "Although it was observed that the TLR4 antagonists did not protect against SN-38 in our cell cytostasis results, this is consistent with studies showing that TLR4 is required for healing in colitis." (PMID 35867263, 2023). "Expression of NF-κB, TLR4, Myd88, and downstream molecules such as TNF-α, IL-6, and IL-1β was effectively reduced by SGP-H, which improved the secretion of anti-inflammatory cytokines including IL-20 and IL-10 in the colon tissue and serum of DSS-induced colitis mice." (PMID 37836386, 2023). "Thus, it appears that MT improves clinical and histopathological traits in DSS-induced colitis in WT, but not in TLR4 KO mice." (PMID 36421432, 2022). "The sequel of events triggered by TLR-4 activation, including NF-kB and NLRP3 activation, and the release of IL-1β, IL-6, and TNF-α, are considered the most involved in persistent intestinal inflammation triggering and maintenance during colitis, and HIV-1 Tat-induced diarrhea." (PMID 36009057, 2022). "The severe acute colitis in AKR1B8 KO mice is featured with high bacterial penetration into mucosa and distant organs, hyper-infiltration of basophils and neutrophils, and activation of innate TLR4 signaling pathway and subsequent production of inflammatory cytokines IL1β and IL6." (PMID 36518763, 2022). "Therefore, in our study, a large number of in vivo and in vitro experiments have been demonstrated that melatonin-mediated MT2 inhibits aeromonas-goblet cell interactions to restore the level of MUC2 production via the LPS/TLR4/MyD88/GSK-3β/ROS/NF-κB loop, further improving colitis in SD mice." (PMID 35355860, 2022). "Therefore, our hypothesis was that CV could act by modulating TLR4 on inflammatory processes and oxidative stress characteristic of IBD in an animal model of DNBS-induced colitis." (PMID 35204289, 2022). "TLR4 is a Toll-like receptor and has been reported to have a repairing effect on DSS-induced intestinal injury and up-regulation of IL6, CCL2 and CSF3, which may also be related to their therapeutic effects on TNBs-induced colitis." (PMID 35831878, 2022). "Ginsenosides are important in inhibiting TLR4/NF-κB/NLRP signal transduction, regulating inflammatory cytokine expression, and inducing immune cell maturation and differentiation to relieve the inflammatory injury in the colonic mucosa of patients with colitis." (PMID 33462754, 2021).
colitis (continued). "Furthermore, we showed that 4-HNE failed to promote DSS-induced colitis in Tlr4−/− mice, supporting that TLR4 signaling is required for the pro-colitic activity of 4-HNE." (PMID 34079800, 2021). "Likewise, oral IAP administration impairs colitis induction in response to Dextran Sulfate Sodium (DSS) in wild-type mice but not in Tlr4−/− mice." (PMID 33494775, 2021). "Similarly, the EPS from the Gram-positive probiotic Bacillus subtilis elicited anti-inflammatory M2 macrophages through TLR4, which was required for EPS-mediated protection from Citrobacter rodentium-induced colitis and limited inflammation during Staphylococcus aureus infection." (PMID 32351514, 2020). "Treatment with IMD did not improve typical colitis symptoms, however, IMD treatment was associated with a significant reduction in the expression of pro-inflammatory mediators TNF-α and IL-8, as well as TLR4." (PMID 31731774, 2019). "Therefore, a rat model of colitis was established in this paper and the changes of NF-κB, TLR4 and TNF-α during the treatment with probiotic VSL#3 were explored, in order to prove the mechanism of action of probiotic VSL#3 in the treatment of colitis and provide clinical references." (PMID 31497551, 2019). "Unlike models of colitis, this protocol directly activates host TLR4-NF-κB inflammation in a relatively short response time (~16–24 h)—a timing that is advantageous for the characterization of host inflammation without the expense of significant alterations in the gut microbiota." (PMID 29017607, 2017). "In states like IBD, wherein TLR4 expression does not shut off, as would be the case in a self-limited colitis, changes in epithelial function and the microbiota may contribute to the perpetuation of inflammation." (PMID 26755160, 2016). "In this context, TLR4 expression was decreased by L. reuteri in the intestine of rats with NEC, by L. rhamnosus and Lactobacillus acidophilus in mice with alcoholic liver disease, and also by LGG and other Lactobacillus and Bifidobacterium in the colon of rats with colitis." (PMID 27820846, 2016). "Our previous study has shown that high expressions of TLR2, TLR4, and TLR9 in the colonic mucosa of experimental colitis rats and a positive correlation between intestinal damage degrees, which implied TLR2, TLR4, and TLR9, prompt the immune injury of murine intestinal in experiment colitis." (PMID 25276470, 2014). "Two recent studies showed independently that TLR4 may not be the culprit in the pathogenesis of commensal-dependent colitis in IL-10−/− mice." (PMID 20803699, 2010). "In this context, PPAR-α agonists, such as PEA, may mediate TLR-4 down-regulation and efficiently suppress the inflammatory process similar to the evidence observed in vitro, clinical studies, endotoxin induced-uveitis rat model, and DSS-induced colitis mice model." (PMID 36009057, 2022). "In addition, to some degree, different levels of Asp administration decreased the gene expression of TLR4 and MYD88 as well as the TNF-α and IL-6 contents in the UC mice, suggesting that Asp could alleviate colitis in mice by regulating the secretion and expression of inflammatory cytokines." (PMID 36145082, 2022). "However, α-TREM-1 treatment did not alleviate colitis in Tlr4- and Myd88-KO mice." (PMID 33767714, 2021). "Moreover, E. coli strain Nissle 1917 has been shown to ameliorate DSS colitis in C57BL/6 WT mice, but not in mice deficient in TLR2 or TLR4, suggesting that activation of both TLR2 and TLR4 signaling is pivotal for this microorganism in order to exert its beneficial effects." (PMID 24062746, 2013). "Consistent with our findings, Gal-9 did not alter DSS-induced colitis severity, but alleviated TNBS induced colitis by inhibiting the TLR4/NF-κB pathway underscoring its context-dependent effects." (PMID 39951917, 2025). "IAP requires TLR4 signaling to mediate its anti-inflammatory effects, as IAP ameliorated colitis and inhibited IL-6 and TNF-α production in WT but not in TLR4-KO mice." (PMID 34944428, 2021).
colitis (continued). "The inhibition of TLR4 signaling by TAK-242, a small-molecule-specific inhibitor of TLR4 signaling, during dextran sulfate sodium salt (DSS)-induced colitis attenuates intestinal inflammation without any overt side effects." (PMID 34025672, 2021). "In non-sterile injury, as in DSS colitis, TLR2/TLR4 activation is driven both by PAMPs from commensal organisms and by LMW-HA released or exposed during injury." (PMID 33552081, 2020). "Compared with the DSS-colitis group, the group treated with 3 mg/kg TAK-242 exhibited no notable change in TLR4 expression, while the groups treated with 10 mg/kg TAK-242, as well as 5-ASA, exhibited a marked downregulation of TLR4." (PMID 32762699, 2020). "Unlike WT and TLR4-/- mice, the severity of DSS-colitis did not improve in TLR2-/- animals after BF colonization." (PMID 28683149, 2017). "Our results showed that BF ameliorated DSS-induced colitis through the TLR2 signal pathway, but not the TLR4 pathway." (PMID 28683149, 2017). "DSS-treatment for 8 days resulted in elevated mRNA levels of TLR4 and TLR7, while expression of TLR2 and TLR9 did not change in colitis mice." (PMID 27658624, 2016). "Either TLR2, TLR4, and TLR5 ligands or the PAMP profile was distinctly different in faecal and intestinal biopsy samples from rats with DSS colitis as opposed to controls." (PMID 21647408, 2011). "The absence of TLR4 combined with the application of HnAb resulted in a particularly strong decrease of both the clinical and the histological manifestations of DSS-induced colitis." (PMID 33193406, 2020). "However, HnAb treatment decreased the mRNA expression of TLR4 and MyD88, but not that of TLR2, TLR9, compared to vehicle-treatment in DSS-induced colitis mice." (PMID 33193406, 2020). "However, there has been no report addressing the relationship between TLR4 and Blimp-1 or NLRP12 during the development of colitis." (PMID 27105524, 2016). "To determine whether TLR2 or TLR4 may be involved in the aggravation of acute colitis, we compared macroscopic signs of disease in C57BL/10 wild-type (wt) mice and animals lacking TLR2, TLR4, or both." (PMID 17653282, 2007). "Similarly, E. coli Nissle 1917 ameliorated dextran sulfate-induced colitis and decreased the pro-inflammatory cytokine response in wild-type mice, but not in TLR2 or TLR4 knockout mice, which supports E. coli Nissle 1917 immunomodulation of host TLR2 and TLR4 signaling." (PMID 31847111, 2019). "Notably, E. coli O160:H7 isolate and other pathogenic and unpathogenic E.coli had a similar ability in inducing TLR4-mediated NF-κB activity, implying that difference of O160:H7 with other gram-negative E.coli in promoting sensitivity to DSS-mediated colitis may not depend on LPS." (PMID 31707260, 2019).
atherosclerosis (412 papers, 2007 to 2026). A disease characterized by the build-up of fatty material and calcium deposition in the arterial wall resulting in partial or complete occlusion of the arterial lumen. "In a Apolipoprotein E Knockout (ApoEKO) mouse model, TLR4 deficiency reduced atherosclerosis upon a high fat diet (HFD), confirming a crucial role of TLR-dependent pathways in disease development." (PMID 41155497, 2025). "TLR4 polymorphisms are also associated with other health conditions, such as atherosclerosis and cardiovascular events." (PMID 40076851, 2025). "TLR4 has been implicated in the regulation of mitophagy in conditions such as atherosclerosis, heat stroke-induced brain injury, and acute pancreatitis-associated splenic injury, although its specific role in AF is not fully understood." (PMID 41357167, 2025). "While some genetic polymorphisms in TLR4 show inconclusive effects on atherosclerosis, TLR4 or MyD88 deficiency in animal models reduces plaque formation." (PMID 40943409, 2025). "EGCG exerts its anti-inflammatory effect in macrophages as well, where at a concentration of 1 μM, it decreases the expression of TLR4, which is implicated in all the inflammatory stages of atherosclerosis." (PMID 41228388, 2025). "Endothelial inflammatory responses mediated by TLR4 are involved in the progression of atherosclerosis associated with diabetes mellitus." (PMID 41181587, 2025). "Our previous investigations have provided evidence for TLR4 role in human atherosclerosis and associated complications." (PMID 38445291, 2024). "Its mechanism of action against atherosclerosis is closely associated with the targeted negative regulation of TLR4 through increased miR-140 expression, and the suppression of TLR4/NF-κB/VEGF signaling pathway activation." (PMID 38635560, 2024). "The increased levels of TLR2 and TLR4 gene expression in the endothelium of human atherosclerotic lesions and the reduced incidence of atherosclerosis in patients with TLR4 polymorphism, suggest a role for TLRs in vascular inflammation." (PMID 37663654, 2023). "According to the Cox regression analysis, only an increase in the number of circulating TLR4-positive intermediate monocytes was associated with an increase in the RR of atherosclerosis progression." (PMID 37569579, 2023). "The human studies also demonstrated that the elevated expression of TLR4 was associated with inflammatory activation in atherosclerosis, and promoted the development of atherosclerosis." (PMID 38041095, 2023). "The TLR4-mediated inflammatory response in ox-LDL-activated platelets is implicated in the pathogenesis of atherosclerosis." (PMID 38304233, 2023). "Caprylate inhibits inflammation through the TLR4/NF-κB signaling pathway, thereby improving atherosclerosis in ApoE-deficient mice." (PMID 36769847, 2023). "TLR4 is well known for its role as an important mediator of the innate immune response and has been linked to atherosclerosis initiation, progression, and plaque destabilization." (PMID 35607519, 2022). "TLR4 signaling pathway has a vital role in lipid accumulation and inflammatory activation in atherosclerosis and is associated with atherosclerotic plaque vulnerability and progression." (PMID 35845572, 2022). "As FcεR1 and TLR4 interactions induce MΦ activation, FcεR1 deficiency attenuates MΦ signal transduction, inflammatory gene expression, apoptosis, and diminishes atherosclerosis." (PMID 33572939, 2021). "Smoking has been linked to increased atherosclerosis and TLR4 has been viewed as a contributor to the pathogenesis of atherosclerosis." (PMID 33995400, 2021). "As mentioned, TLR4 plays an important role in initiating inflammation associated with atherosclerosis." (PMID 32378144, 2021).
atherosclerosis (continued). "Specifically, atherosclerosis-prone ApoE−/− mice deficient in TLR4 or MyD88 have less atherosclerotic plaques associated with a reduction in macrophage recruitment." (PMID 33505393, 2020). "First observations were made for Toll-like receptors (TLRs), genetic deletion of Tlr4 was shown to reduce experimental atherosclerosis in Apoe-deficient mice." (PMID 32588196, 2020). "Recently, TLR4 has been associated with other chronic inflammatory diseases, such as diabetes and atherosclerosis." (PMID 32397494, 2020). "Apolipoprotein E (ApoE)-deficient mice are prone to high-fat diet-induced atherosclerosis, which is reduced in additional TLR4-deficiency or MyD88-deficiency, indicating an important role of TLR4/MyD88 signaling in atherosclerosis." (PMID 32391019, 2020). "A recent study reported that TLR2 and TLR4 deficiency markedly reduced atherosclerosis that was induced by oral bacteria." (PMID 31583048, 2019). "Excess immune activation caused by obesity is of particular concern for vascular health, as activation of TLR4 causes monocyte recruitment and conversion to foam cells, driving the progression of atherosclerosis." (PMID 31214598, 2019). "Multiple studies have shown the involvement of TLR-4 in thrombosis-associated ischemic diseases, including stoke, myocardial remodeling and atherosclerosis." (PMID 31682263, 2019). "In other mouse models, TLR4 deficiency in atherosclerosis-prone ApoE-deficient mice fed a HFD showed significant reduction of aortic plaque areas, plaque lipid content, macrophage infiltration, and circulating levels of proinflammatory cytokines." (PMID 31582899, 2019). "Compelling evidences indicate that HMGB1, TLR4, and IL-1β are implicated in the progression of atherosclerosis." (PMID 30881312, 2019). "Recently, studies have suggested that TLR4 mediated inflammatory responses are associated with the occurrence of atherosclerosis, heart disease, and other vascular diseases." (PMID 29367652, 2018). "Gene mutation and gene knockout in TLR2 or TLR4 decrease TLR4 signaling and ameliorate atherosclerosis." (PMID 29357881, 2018). "In agreement, humans with TLR4 mutations, which lead to reduced receptor signaling and depressed inflammatory response, are also less susceptible to atherosclerosis." (PMID 30666212, 2018). "We highlight our work on the oral pathogen Porphyromonas gingivalis and discuss the role of microbial modulation of lipid A structures in evasion of TLR4 signaling and resulting systemic immunopathology associated with atherosclerosis." (PMID 28348558, 2017). "Our results are consistent with the theory that TLR4 rs11536889 variant genotypes act as a risk factor for atherosclerosis development via increased TLR4 production." (PMID 28002812, 2017). "Previous studies have reported that the disease associations of TLR4 with chronic inflammatory disease include atherosclerosis, asthma, and rheumatoid arthritis." (PMID 28912808, 2017). "TLR4 is ubiquitously expressed in cardiovascular cells; TLR4 signaling is also associated with vascular inflammatory pathologies, such as atherosclerosis." (PMID 28976997, 2017). "In contrast to the effect of TLR2-deficiency on P. gingivalis-induced atherosclerosis, we demonstrate that TLR4-deficiency leads to increased disease severity, indicating a protective role for TLR4 signaling in P. gingivalis-induced atherosclerosis." (PMID 28348558, 2017). "Considering the complex nature of atherosclerosis, it suggests that TLR4 Asp299Gly polymorphism has only a minor impact on the pathogenesis of CHD." (PMID 28793055, 2017). "A single nucleotide polymorphism TLR4 Asp299Gly (rs4986790) has been reported to be associated with lower levels of proinflammatory serum markers, many of which have been implicated in atherosclerosis." (PMID 28793055, 2017). "The expression of TLR4 is increased in atherosclerotic plaques of animal models, and atherosclerosis-associated inflammation is alleviated in TLR4 knockout mice." (PMID 28420166, 2017).